C3 (complement C3)
Diseases named in the same sentence as C3 in open-access papers (continued):
Sharing a sentence is not in itself a finding about the gene and the disease.
pemphigoid gestationis (1 paper, 2023). A rare pregnancy-associated autoimmune skin disease that is characterized by an itchy rash that develops into blisters. "Anti-BP180 ELISA is a particularly useful tool for diagnosing patients with pregnancy-associated pemphigoid gestationis, who exhibit low levels of IgG binding to BP180 antigens which is often detectable only with the C3 conjugate in DIF." (PMID 38074463, 2023).
pemphigus erythematosus (1 paper, 2023). "Chief cutaneous findings of pemphigus erythematosus, along with positive deposits of IgG, IgM, and C3 in an intercellular pattern and along the DEJ, were suggestive of diagnosis." (PMID 38957191, 2023).
pemphigus herpetiformis (1 paper, 2022). Pemphigus herpetiformis is a rare autoimmune bullous skin disorder that is considered a clinical variant of pemphigus. "However, the positive rates of deposition of IgA and C3 in the intercellular space of the epidermis in pemphigus herpetiformis are 6.3% and 44.4%, respectively." (PMID 35625932, 2022).
Peritoneal Fibrosis (1 paper, 2022). Disorder characterized by a wide range of structural changes in PERITONEUM, resulting from fibrogenic or inflammatory processes. "We demonstrate that the gene expression of the complement molecules (C2, C3, C5, C6) and the inhibitory molecules (CD55) is increased in the abdominal wall of the CHX-induced mouse model of peritoneal fibrosis." (PMID 36359246, 2022).
placental abruption (1 paper, 2017). Vaginal bleeding preceding the 20th week of gestation. "For example, patients with placental abruption exhibit a disordered activity of complement system, especially that of C3-activator." (PMID 28542608, 2017).
posterior uveitis (1 paper, 2023). Inflammation of the choroid as well as the retina and vitreous body. "In the case of posterior uveitis, upregulation of both C3 and CFH genes could be an indicator of a blood-retinal breakdown (BRB)." (PMID 38187376, 2023). "We also evaluated the estimation of major alternative complement pathway components, namely, C3 and CFH, in the aqueous and vitreous humor of anterior and posterior uveitis patients, as well as their expression and regulation by miRNAs." (PMID 38187376, 2023). "Downregulation of C3 and CFH mRNA in the peripheral blood was shown by quantitative PCR in the group of anterior uveiits (AU), while the opposite result was found in the group of posterior uveitis (PU)." (PMID 38187376, 2023).
protein deficiency (1 paper, 2023). "The remaining 3 patients have factor H –related protein deficiency (n = 1); factor I deficiency (n = 1); and C3 deficiency (n = 1)." (PMID 37559153, 2023).
pseudoexfoliation syndrome (1 paper, 2020). "Next to the involvement of CLU in pseudoexfoliation syndrome, C3 was found to be significantly upregulated in aqueous humor in eyes of patients with pseudoexfoliation syndrome indicating an important role for complement activation during this disease." (PMID 33362763, 2020).
Pseudomonas infection (1 paper, 2020). Infections with bacteria of the genus pseudomonas. "Therefore, the increase in susceptibility to Pseudomonas infection we observed in c3a.1−/− larvae expressing wild-type rac2 is likely predominantly due to a neutrophil-intrinsic function of C3, possibly due to the reduction in numbers of neutrophils found at the infection site." (PMID 32973200, 2020).
pulmonary embolism (1 paper, 2020). The obstruction of the pulmonary artery or one of its branches by an embolus, sometimes associated with infarction of the lung. "One of the patients in our series presented concurrent pulmonary embolism and cutaneous intravascular thrombi, whereby DIF showed the deposition of IgM, C3, and fibrinogen within superficial-to-deep dermal blood vessel walls." (PMID 33053817, 2020).
pyelonephritis (1 paper, 2015). An inflammatory process affecting the kidney. "The immune response profile revealed high quantities of complement component C3, which was previously linked to augmented risk of pyelonephritis via invasion of renal tubular cells." (PMID 25889401, 2015).
Pyoderma (1 paper, 2024). Any manifestation of a skin disease associated with the production of pus. "In contrast to other studies, pyoderma was less common associated with PIGN in our study, still we found ASO positivity to be as high as 77.80% and half of the cases with pyoderma had low serum C3 that was similar to other study." (PMID 39356841, 2024).
relapsing-remitting MS (1 paper, 2019). "A more recent study defined elevated plasma C4a levels and elevated C3 levels in CSF of patients with active relapsing-remitting MS (RRMS) potentially providing furthermore follow-up markers for therapeutic efficacy." (PMID 31780883, 2019).
Renal atrophy (1 paper, 2025). Atrophy of the kidney. "A new renal biopsy revealed the progression of FSGS up to 40% of glomeruli, with renal atrophy, interstitial fibrosis associated with severe interstitial infiltrate, and glomerular deposits with segmentary distribution of IgM (3/4), C3, C4, C1q (2/4), and arteriolar deposits of C3." (PMID 40282423, 2025).
retinal detachment (1 paper, 2018). An eye emergency condition which may lead to blindness if left untreated. "In retinal detachment models in mice, deficiencies in key complement components (i.e., Factor b, or C3) resulted in a decreased number of apoptotic cells compared to wild type C57BL/6J mice with retinal detachment." (PMID 29497373, 2018).
retinal ischemia (1 paper, 2016). A ischemic disease that involves the retina. "While there exists sufficient evidence of activation of the downstream complement cascade including C3 following retinal ischemia, our results suggest C1q may be acting in a cascade-independent role." (PMID 27008854, 2016).
retinal vasculitis (1 paper, 2024). Inflammation of the retinal vasculature with various causes including infectious disease; lupus erythematosus, systemic; multiple sclerosis; behcet syndrome; and chorioretinitis. "Spontaneous inflammation seen in C3 knockout mice may play a role in the pathogenesis of retinal vasculitis seen clinically in patients receiving intravitreal injections of a profound C3 depleter pegcetacoplan." (PMID 38675477, 2024).
retroperitoneal fibrosis (1 paper, 2021). "The mean serums C3 and C4 were normal in a group of renal pelvis or ureter involvement, abnormal renal radiological findings, and renal parenchymal lesions accompanied by retroperitoneal fibrosis." (PMID 33827676, 2021).
Rickettsiosis (1 paper, 2023). A group of infectious diseases that is caused by Rickettsia. "To determine if complement influences Rickettsia proliferation in these macrophages, we infected RAW264.7 cells with the causative agent of Rickettsia parkeri rickettsiosis in the presence (NMS) or absence (C3−/− MS) of functional complement." (PMID 37855623, 2023).
schizoaffective disorder (1 paper, 2023). "In addition to genetic findings, studies have reported that individuals with acute SZ or schizoaffective disorder have increased levels of peripheral complement components C3, C3b, and C4." (PMID 37656188, 2023).
septic peritonitis (1 paper, 2015). Septic peritonitis is an inflammatory condition of the peritoneum that occurs secondary to microbial contamination. "Complement plays an important role in host defense mechanisms, and our finding here is also in accord with a previous study in which it was shown that C3 deficiency, but not CR2-Crry treatment, increased susceptibility to infection in a model of septic peritonitis." (PMID 26714866, 2015).
Shock (1 paper, 2012). The state in which profound and widespread reduction of effective tissue perfusion leads first to reversible, and then if prolonged, to irreversible cellular injury. "In a clinical study of 48 patients (19 with septic shock), those with septic shock had markedly decreased levels of C3, C4, and total complement activity as measured by the 50% hemolytic complement (CH50) assay." (PMID 23049598, 2012).
skin changes (1 paper, 2016). "In our case, the patient had typical skin changes, nail-fold capillary abnormalities, antinuclear antibodies detected by biochemical and serologic tests, elevated Ig E and Ig G, and low level of complement (C3)." (PMID 27142369, 2016).
sleep disorder (1 paper, 2025). A change from the patient's baseline sleeping pattern, in the hours slept and/or an alteration/dysfunction in the stages of sleep. "In contrast, the sleep disorder group showed significantly lower levels of peripheral lymphocyte count, CD3+ T cell proportion, CD4+ T cell proportion, immunoglobulin G, immunoglobulin A, immunoglobulin M, Complement C3, and Complement C4 (all P < 0.001)." (PMID 41584611, 2025).
Ss (1 paper, 2024). "Our data here clearly shows that there is a link between lower levels of C1q, C4b, MBL, C5a, C3, C3b/iC3b factor B and factor D and the presence of Ss infection." (PMID 38564496, 2024).
Stillbirth (1 paper, 2025). Death of the fetus in utero after at least 22 weeks of gestation. "Early declines in C3 were predictive of stillbirth, underscoring the importance of continuing immunosuppression and complement monitoring throughout pregnancy." (PMID 41003109, 2025).
T-cell leukemia (1 paper, 2017). A malignant disease of the T-lymphocytes in the bone marrow, thymus, and/or blood. "Evidence for a CR2 and CR1 function in T cells was their 3- to 10-fold enhancement of C3-dependent HIV infection in the HPB-ALL T cell leukemia cell line." (PMID 28814669, 2017).
thoracic aortic aneurysm (1 paper, 2025). An aneurysm formed in the wall of the proximal portion of the descending aorta proceeding from the arch of the aorta. "Moreover, in our work, we have shown that SMCs isolated from the tunica intima actively secrete proteins C3 and C4B, therefore, it can be assumed that the classical and alternative pathways of the complement system are activated with thoracic aortic aneurysm." (PMID 40695950, 2025).
thyroid cancer (1 paper, 2023). "Further validation was required to validate the hypothesis that IgG and C3 released by thyroid cancer cells expose patients to IgAN risk." (PMID 37670254, 2023). "In thyroid cancer tissues, researchers discovered C3c, a fragment of complement component C3." (PMID 37670254, 2023).
uterine corpus endometrial carcinoma (1 paper, 2019). A endometrial carcinoma (disease) that involves the body of uterus. "We observed similar features in the uterine corpus endometrial carcinoma dataset: the genes with the highest frequency included SOX17 and C3 (8%), PAX8, MME and ESR1 (7%)." (PMID 31879572, 2019).
infection (453 papers, 2007 to 2026). The state of being infected such as from the introduction of a foreign agent such as serum, vaccine, antigenic substance or organism. "First, we found that the infection of S. aureus resulted in dramatic weight loss, which can be mitigated by the deletion of C3." (PMID 40294039, 2025). "Further validation in large and well-designed studies is needed to clarify the association of C3 with infection severity and its potential as a prognostic biomarker." (PMID 41291834, 2025). "Analysis of the susceptibility of wild-type, PTX3-deficient, complement C3-deficient and Ptx3-/-/C3-/- mice to infection revealed that PTX3 exerts its protective effects against K. pneumoniae in a complement-independent manner." (PMID 40313930, 2025). "C3 NIMA female mice postpartum after pregnancy sired by C3–/– males, with loss of C3+/– MMcs, contained only background serum C3 levels and infection susceptibility comparable with C3–/– controls." (PMID 39541162, 2024). "To verify importance of C3+/– MMcs, we evaluated C3 levels and infection susceptibility after MMc depletion using antibody- or pregnancy-induced MMc displacement in male and female C3 NIMA mice, respectively." (PMID 39541162, 2024). "High C3a and C5a levels on admission are associated with severe infection, as are decreases in serum C3 and C4." (PMID 39202695, 2024). "Decreased levels of C3 lead to a reduction in the body’s ability to fight infection and a near loss of C3-mediated lysis and clearance of circulating immune complexes." (PMID 38026392, 2023). "C3-deficient mice infected by Streptococcus pneumoniae exhibited significantly infection in the lungs and bloodstream, leading to an overwhelming inflammatory response and decreased survival times." (PMID 35281048, 2022). "The comparison of susceptibility of wild-type, Ptx3-/-, C3-/- and Ptx3-/-/C3-/- mice to the infection showed that PTX3 acted in a complement-independent manner." (PMID 34093560, 2021). "Despite these challenges, direct C3 targeting appears an attractive target in severe infection with highly pathogenic coronaviruses." (PMID 32643798, 2021). "Our findings are consistent with previous studies that found suboptimal C3 levels at time of SLE diagnosis or decreased total complement activity (CH50 < 30 U/mL) to be associated with higher infection risk." (PMID 32972440, 2020). "In a mouse intra-gastric model of infection with L. monocytogenes, it was observed that L. monocytogenes caused the production of C3 in intestinal mucosa, showing that C3 can be in close proximity to intestinal cells in the course of infection." (PMID 32274388, 2020). "We also categorically examined the risk of an infection in patients with low C3 (C3 < 83 mg/dL per reference range) compared to those with a normal C3 level." (PMID 32972440, 2020). "Infection of C3 deficient mice with SARS-CoV revealed that the loss of complement activity resulted in milder disease outcomes." (PMID 32733480, 2020). "Among the common proteins that were increased in abundance, all (Saa1, Lrg1, Hpx, Hp, Itih4, Serpina3n, Fga/b/g, Cp, and C3) were associated with the acute-phase response to infection." (PMID 32843537, 2020). "Studies in deficient mice for C3 have shown that the activation of C3 is essential for viral clearance and protection against infection." (PMID 33334050, 2020). "A mouse model of S. aureus septic arthritis showed that deficiency in C3 increases susceptibility to infection, potentially through decreased peritoneal macrophage phagocytosis." (PMID 33542723, 2020). "In a clinical case report, an inadequate response to infection with signs of systemic depletion of complement (dropping C3 and C4 levels) has been associated with the development of acute kidney injury and multiple organ failure in a 17-day old newborn." (PMID 30949180, 2019).
infection (continued). "Infection of C3 deficient mice led to uncontrolled parasite growth, acute mortality, and reduced antibody production, indicating that both the presence of C3, and the ability of the parasite to inactivate C3, was protective." (PMID 32010145, 2019). "In this study, intraperitoneal infection of C3 deficient mice determined that C3 was protective in vivo." (PMID 32010145, 2019). "All C3 deficient mice infected with tachyzoites or tissue cysts were more susceptible to infection, the result of unregulated parasite proliferation." (PMID 32010145, 2019). "We, therefore, used our CEACAM1-humanized mouse model in combination with deficiencies in C3 (C3−/-), C5 (C5−/-), C3aR1 (C3ar1-/-) C5aR1 (C5ar1−/-) or C5aR2 (C5ar2−/-) to monitor Nme nasal colonization following intranasal infection with 105 CFU." (PMID 31274379, 2019). "This study revealed that C3 depletion is associated with a poor prognosis due to dysregulated coagulation and increased susceptibility for infections." (PMID 30949180, 2019). "Gene expression analyses were performed on liver samples taken six hours post-infection for both wild type mice, and mice rendered deficient for complement component 3 (C3) by gene targeting." (PMID 28588308, 2017). "C3 deficiency in humans correlates with recurrent infections of the upper and lower respiratory tract." (PMID 28418930, 2017). "The viral load was found to be higher during the initial phase of the infection i.e., at day 4 p.i., in complement deficient (C3-/-, C4-/- and FB-/-) as well as WT mice." (PMID 28301559, 2017). "It has been reported that a low level of complement C3 is an independent risk factor for the development of severe infection in SLE patients." (PMID 29267496, 2017). "In patients with ascites fluid that contains protein levels <1 g/dL and/or C3 levels < 13 mg/dL, there is a predisposition for infection." (PMID 26618012, 2015). "Changes in C3 activation over time can also be caused by various factors related to immune defense in case of infection." (PMID 25393287, 2014). "While inhibitors such as compstatin can potently inhibit C3, effectively shutting down all three complement pathways, this has the potential to predispose individuals to an increased risk of infection." (PMID 25202312, 2014). "The unfavorable consequences of C3 deficiency became apparent after approximately ten days in the course of high-dose C. psittaci infection, and even later in low-dose infection." (PMID 23189195, 2012). "By multiple inoculation routes, ectromelia virus caused increased mortality by 7 to 10 days post-infection in C57BL/6 mice that lack C3, the central component of the complement cascade." (PMID 19112490, 2008). "To characterize how complement protects the host from lethal infection, we analyzed the impact of C3 deficiency on the kinetics of viral spread." (PMID 19112490, 2008). "Deficiency of C3, C4, or FB resulted in acute lethal infection, establishing a requirement for multiple complement pathways in host defense against this pathogen." (PMID 19112490, 2008). "In 3- to 4-week-old mice, C3-deficient animals exhibit reduced survival following infection." (PMID 41031883, 2025). "Whether C3 blockade significantly increases infection risk or impairs immune surveillance in already immunosuppressed transplant recipients remains unclear and requires further study." (PMID 41031895, 2025). "This may be attributable to the excessive degradation of C3 already initiated during the early infection phase, therefore causing C3a levels in the Sap2‐273L‐infected group to remain consistently low throughout the infection process." (PMID 37211685, 2023). "From the perspective of infection risks caused by encapsulated bacteria, in vitro results with Hib, meningococci and pneumococci indicate potential advantages of AP inhibitors over C3 and C5 inhibitors, in particular, when treatment is combined with prior vaccination of patients." (PMID 36578495, 2022).